ENSG00000284956 (novel protein)
Gene: Protein-coding gene on chromosome 8 (23,084,403 to 23,115,536, forward strand). Ensembl gene ENSG00000284956.
Genetic constraint (gnomAD): Loss-of-function variants: 1 observed, 1.22 expected, observed/expected ratio (o/e) 0.82, 90% interval 0.24 to 1.87. That is too few expected variants to judge how well the gene tolerates losing a copy. Missense variants: 24 observed, 25.34 expected, observed/expected ratio (o/e) 0.95, 90% interval 0.69 to 1.33. Synonymous variants: 7 observed, 8.1 expected, observed/expected ratio (o/e) 0.86, 90% interval 0.49 to 1.59.